GP2 (glycoprotein 2)
Diseases named in the same sentence as GP2 in open-access papers (continued):
Sharing a sentence is not in itself a finding about the gene and the disease.
lupus (1 paper, 2025). "More intriguingly, expression of DTA or loss of IRF4 in activated B-1 cells resulted in the production of IgG against protein autoantigens that are less specific for lupus including C1q, collagen, laminin, Gp2, PR3, and MPO." (PMID 41445737, 2025).
metastatic cancer (1 paper, 2019). A carcinoma which has spread from the original site of growth to another anatomic site. "Combined analysis with GP2 was intended to improve the effectiveness of our EV-based test, however an even lower number of metastatic cancer patients exhibited elevated GPC1-GP2 EV counts compared to mean counts in BPD patients than GPC1 EV counts (2 of 30 patients compared to 9 of 30 patients)." (PMID 30800217, 2019).
pulmonary disease (1 paper, 2017). "The deletion of gene US4 (gp2) in EHV-1 Ab4 resulted in its attenuation, and the generated virus conferred protection against pulmonary disease in mice after challenge with wt virus." (PMID 29312962, 2017).
Salmonella Infections (1 paper, 2018). Infections with bacteria of the genus SALMONELLA. "In order to elucidate the underlying molecular mechanisms of host specificity in Salmonella infection, we investigated the role of the intestinal host cell receptor zymogen granule membrane glycoprotein 2 (GP2), which is recognized by FimH adhesin of type 1 fimbriae found in Enterobacteriaceae." (PMID 30186250, 2018). "In our study, expression of GP2 isoform 4 in HEp-2 cells resulted in increased Salmonella infection but expression of GP2 isoform 2 in HEp-2 cells resulted in decreased infection, though expression of both GP2 isoforms was similar as measured by flow cytometry." (PMID 30186250, 2018).
infection (45 papers, 2008 to 2025). The state of being infected such as from the introduction of a foreign agent such as serum, vaccine, antigenic substance or organism. "As we believe the gp2-gp3-gp4 encode for tail fibers involved in adhesion, an attempt was made to correlate the sequencing data of their putative products with the host infection pattern of the studied phages." (PMID 32138347, 2020). "This indicates a complex interplay of glycoproteins on cells and that different GP2 isoforms can affect infection by different FimH variants." (PMID 30186250, 2018). "A previous study by Wong and colleagues demonstrated that passaging of VSV-EBOV lacking the MLD in the presence of a CatB inhibitor rapidly selected for mutations in GP1 or GP2 that conferred resistance, i.e., allowed efficient infection of target cells in the presence of inhibitor." (PMID 31618932, 2019). "Finally, we analyzed whether GP2 expression results in higher infection by Salmonella FimH variants." (PMID 30186250, 2018). "At 48 h post-infection, expression of a range of PRRs and other genes, including those encoding C-type lectins, scavenger receptors, complement components, TLRs, NLRs, and GP2 was strongly suppressed, implying that host immunity may be downregulated or compromised in response to Chromera infection." (PMID 29321691, 2018). "Confocal microscopy demonstrated that at 4 h after infection, a proportion of the STm‐containing epithelial cells stained positive for GP2." (PMID 39807570, 2025). "In the M-cell deficient enteroids (- RANKL), the presence of Salmonella stimulated an increased expression of Gp2 by 24 hours post-infection (compare circles and triangles in the plots)." (PMID 39040600, 2024). "Our results thus indicate that mAbs CM10, CM11.1, and CM12.1 alltarget an epitope within the GP2 N terminus, one that overlaps with epitopes ofpreviously reported protective mAbs isolated from natural infection and animalimmunizations." (PMID 38832790, 2024). "LCMV induces Abs against N and GP2 soon after infection, reaching higher titers, whereas nAbs exclusively target GP1 and remain undetectable for the first two months after infection in mice." (PMID 38543848, 2024). "The expression of full-length MARV-GP and the GP2 cleavage product was already detectable eight hours after infection, indicating proper early transcription driven by the synthetic MVA-specific promoter PmH5." (PMID 39771978, 2024). "The conditions of an MOI of 20 (BacD4D-2GP2-2GP4) and 3 day post infection showed higher expression levels of the ectodomain of His-tagged GP2-gp64TM-CTD and His-tagged GP4-gp64TM-CTD fusion proteins." (PMID 38005998, 2023). "Among our list of RecA-interacting and ChmA-interacting proteins, we identified six proteins (gp2, gp61, gp63, gp64, gp148 and gp375) that clearly localized to the nuclear shell upon ΦPA3 infection of P. aeruginosa cells." (PMID 37667030, 2023). "Considering individual parasite, only the infection with Giardia lamblia (G. lamblia) was found to be statistically higher among Gp2 in comparison to Gp1." (PMID 36944683, 2023). "We demonstrate that GP2 is involved in the regulation of colonization and infection and thus represents a molecule of interest for the prevention or treatment of disease." (PMID 35020452, 2022). "We assume that, here, GP2 binds to bacteria and interferes with bacterial adhesion/infection to the intestinal wall and thus controls bacterial infection." (PMID 35020452, 2022). "Of note, GP2-specific mAbs have been isolated after infection/immunization with either Old World or New World arenaviruses: in line with the sequence conservation of GP2 these antibodies are able to bind several species of arenaviruses." (PMID 34578349, 2021). "This indicates that Atoh8 lox/VilCre mice with higher Gp2 expression also had functional characteristics during an infection." (PMID 34502262, 2021).
infection (continued). "Despite the distinct responses of coral larvae to Chromera and Symbiodinium, one common characteristic was downregulation of the gene encoding the coral homolog of pancreatic secretory granule membrane major glycoprotein GP2 at 4 h post-infection." (PMID 29321691, 2018). "Further work is necessary to study expression of GP2 isoforms in different intestinal parts and in different cell types as well as to compare healthy and diseased hosts to clarify roles of different GP2 isoforms in infection." (PMID 30186250, 2018). "In FimH variants which were not able to recognize glycoproteins, an alternative adhesion/infection process was triggered which resulted in enhanced infection of GP2-expressing cells." (PMID 30186250, 2018). "In the case of infection with a competent Symbiodinium strain, GP2 expression had returned to baseline levels by 12 h post-infection, whereas the gene was further downregulated 48 h after Chromera infection." (PMID 29321691, 2018). "It is very well possible that the full-length gp2 protein is involved in the induction of CCL2 in the early stage of infection." (PMID 28241864, 2017). "Whereas Gp2 is indispensable for T7 growth in E. coli, we show that Gp5.7 is required for optimal infection outcome." (PMID 28486695, 2017). "Although very unique, the early genome region encodes one protein, gp2, which is conserved in PaP3, PA11 and the entire phiKMV genus, suggesting a critical role in infection." (PMID 26594207, 2015). "The data indicated that at 24, 48 and 72 h post-infection nsp2, GP2, GP4, GP5, M and N proteins appeared less abundant in 3-AB treated cells than the non-treated cells." (PMID 25614100, 2015). "The hyper-glycosylation mutant localized on GP2, E379N/A381T, exhibited a unique feature during primary neuron infection, with an initial drop in virus titer up to the 16 h time point followed by constant linear growth through later time points." (PMID 23308183, 2013). "This supported the hypothesis that GPC processing to GP1 and GP2 is incomplete at the initial stage of infection." (PMID 38916347, 2024). "The slightly higher GP2 levels in the batches can be explained as indicated by other studies which show that GP1 may get dissociated from GP2 during the infection process resulting in a slightly higher GP2 content." (PMID 38916347, 2024). "Because structurally related human proteins Uromodulin and GP2 bind to bacteria and control infection, we hypothesized that omcin genes have a similar function." (PMID 39309883, 2024). "Preincubation of the ETEC pathotype with GP2 reduced the infection of cell lines." (PMID 35020452, 2022). "The endosomal entry of EBOV is by GP1, while the low pH membrane fusion is coordinated by GP2 using Neimann-Pick C1 protein (NPC1), and thus implicated as major pathogenic determinants for infection and the main target for the development of a vaccine for Ebola virus." (PMID 31569539, 2019). "Using HEp-2 cells, infection was FimH variant-specific but with few exceptions independent of GP2 expression in general or independent of one human GP2 isoform." (PMID 30186250, 2018). "We finally explored the GP2 – FimH interaction by infection assays using the isogenic strains." (PMID 30186250, 2018). "While cultures infected with the lower inocula (10^5 and 10^6) had a similar proportion of M cells compared to uninfected control cultures, monolayers infected with the highest inoculum (10^7) showed a near doubling of the number of GP2+ cells within 1 h after infection." (PMID 26820624, 2016). "However, cell line infection assays revealed fundamental differences: using HEp-2 cells, infection was also FimH variant-specific but mainly independent of human GP2." (PMID 30186250, 2018). "Additionally, 46 genes encoding for secreted proteins may serve as markers in blood for the degree of protection (Cxcl9, Gp2, and Pla2g2d), intensity of infection (Retnla, Saa3, Il6, and Il1b), or adaptive recall responses (Ighg, C1qb)." (PMID 28243609, 2017).
infection (continued). "Antibodies binding to the nucleoprotein (NP) and the glycoprotein-2 subunit (GP-2) are elicited early after infection and reach high titers, whereas neutralizing antibodies target exclusively GP-1 and remain undetectable for the first 40–60 days after infection." (PMID 26587982, 2015). "Global transcriptome and phosphoproteome analysis in E. coli under udk overexpressing conditions and during wild-type T7 and T7Δ0.7 infections might provide further insights into overexpressed Udk-mediated antagonism of Gp2 function in E. coli during T7 phage infection." (PMID 23242801, 2013). "The two-pronged strategy used by Gp2 to inhibit the host RNAp, through occlusion of dwDNA from binding to the dwDBC and appropriation of a σ70-specific domain, leads to highly efficient inhibition of Eσ70-dependent transcription from very strong early T7 promoters to ensure successful infection." (PMID 22819324, 2012). "Infection with MDR pathogens, as seen in GP2 and GP6, induced oxidative stress and persistent inflammation, impairing tissue repair." (PMID 40672366, 2025). "The highest frequency of IgG molecules targeted the C-terminus of GP2 epitope encompassing the CHR and the MPER, which were long-lasting and observed from 12 to 60 months post-infection in these survivors." (PMID 39285186, 2024). "A similar strategy is likely to be employed by the major receptor for FimH‐positive bacteria in the gastrointestinal tract, glycoprotein 2 (GP2), to counteract infection by type I‐piliated Escherichia and Salmonella strains." (PMID 33196145, 2020). "The principal finding of this study is that T7 requires, in addition to Gp2, another RNAP inhibiting small protein to temporally control the activity of the host RNAP during infection." (PMID 28486695, 2017). "Infection of Escherichia coli by the T7 phage leads to rapid and selective inhibition of the bacterial RNA polymerase (RNAP) by the 7 kDa T7 protein Gp2." (PMID 28486695, 2017). "However, the gI/gE/gp2 mutant exerted a weaker CPE than wild-type EqAHV1 YM2019 and other mutant strains at a multiplicity of infection (MOI) of 0.1." (PMID 39021566, 2024). "The ΔTK/gp2 or ΔUL24/TK/gp2 infection groups did not exhibit any significant animal mortality, clinical signs, abnormal body weight changes, or pathological damage to the lung or brain tissues during the fourteen-day experimental period." (PMID 39021566, 2024). "Particularly, PRRSV strains with a K160 in GP2 efficiently infect MARC-145, PK15-pCD163, and PAMs while mutants with a K160I substitution in GP2 infect MARC-145 but not PK15-pCD163 and PAMs, even though this mutant still requires CD163 for infection." (PMID 36560826, 2022). "Using HEp-2 cells (expressing and not expressing GP2) an infection pattern similar to the static GP2 adhesion assay was visible." (PMID 30186250, 2018). "In HEp-2 cells, there was no general trend that GP2 expression supports infection indicating that the surface of HEp-2 cells already presents sufficient glycoproteins other than GP2 as receptors." (PMID 30186250, 2018). "Although Gp5.7, unlike Gp2, is dispensable for T7 growth in Ec, Gp5.7 is clearly required for optimal infection." (PMID 28486695, 2017). "The absence of Gp2 results in unsuccessful infection because the antiterminated host RNAp moves into regions of the T7 genome that are normally transcribed by the T7 RNAp." (PMID 22819324, 2012). "In other words, overexpression of udk mimics the absence of Gp2 during T7 phage infection and leads to accumulation of anti-terminated transcription from early T7 promoters, which as a consequence abrogates successful T7 phage gene expression and infection." (PMID 23242801, 2013). "One exception is the non-inhibitory gp2, which is conserved in PaP3, PA11 and the entire phiKMVlikevirus genus, suggesting a critical role in infection." (PMID 26594207, 2015).
infection (continued). "GP2, GP3 and GP4 together with non-glycosylated E proteins can form heterotetramers of heterologous proteins in cells that have been infected with PRRSV, which, although non-essential for the formation of PRRSV virus particles, play pivotal roles in the infection process." (PMID 39943200, 2025).
tumor (20 papers, 2005 to 2026). "In a randomized, blinded, controlled phase II trial, the GP2 peptide vaccine was applied in HLA-A2 positive, HER2/neu-expressing tumor (IHC 1–3+), disease-free node positive, and high-risk node negative BC patients enrolled after standard-of-care therapy." (PMID 40333213, 2025). "Trastuzumab increased the sensitivity of the tumor cells to CTL-mediated lysis after stimulation with either GP2 or E75, even in patients with low levels of HER2 expression." (PMID 40333213, 2025). "The GP2 phage-based vaccine has a therapeutic effect in a BALB/c mouse xenograft tumor model by efficiently inhibiting tumor growth and prolonging survival." (PMID 36851313, 2023). "Trastuzumab increased the sensitivity of the tumor cells to CTL-mediated lysis after stimulation with either nelipepimut-S or GP2, even in patients with low levels of HER2 expression." (PMID 32323103, 2020). "VNPs displaying gpD (λ) fused to GP2, a peptide derivative from the overexpressed tumor protein HER2/nue, generated a strong cytotoxic T lymphocyte response that had anti-tumor activity when given prophylactically or therapeutically in a mouse model." (PMID 33066635, 2020). "Our results indicate that the λF7 test construct decorated with the fused peptide gpD::GP2 successfully decreased the tumor size in prophylactic (P < 0.01) and therapeutic (P < 0.05) assays in comparison to the TN buffer." (PMID 30778090, 2019). "Among different mice groups, the gpD::GP2 group was more efficient in inhibition of tumor growth rate compared to the TN buffer (P < 0.01) and λF7 groups (P < 0.05)." (PMID 30778090, 2019). "We think that the observed immunogenicity of the gpD::GP2 phage nanoparticles as both protective and inhibitors of tumor against HER2/neu overexpressing implantable tumor deserves more investigation." (PMID 30778090, 2019). "The analysis of tumor growth curve indicated that the gpD::GP2 group proved to be prophylactically effective as it significantly reduced the growth rate of the tumor (P < 0.0001) compared with TN buffer and the λF7 group (P < 0.01)." (PMID 30778090, 2019). "The CTL responses elicited by vaccination of mice with the gpD::GP2 nanoparticles exhibited a latency in tumor growth and presnetd with superior anti-tumor effects in vivo." (PMID 30778090, 2019). "Interestingly, only the gpD::GP2 chimera in which the GP2 peptide was directly linked to gpD by an in-frame short linker contains GG and GS (T-S-G-S-G-S-G-S-G-S-G-S-G-S-G) flexible space was successfully processed and cross-presented and induced effective anti-tumor CTL responses." (PMID 30778090, 2019). "This is of interest, as aGP2 IgA secreted onto mucosal surfaces might mediate the up-take of GP2-covered bacteria by GP2-bearing M cells of the intestinal follicle-associated epithelium and, thus, partake in the development of severe complications or even pre-tumor stages." (PMID 30233574, 2018). "We prepared different liposomal formulations with GP2 peptide to induce enhanced CTL immune response in a TUBO tumor model of mice." (PMID 29045460, 2017). "raised concerns about the derivation of αGPi​ values, particularly αGP2​, suggesting that it may have had a limited impact on the optimization function, likely due to the low proportion of GP2 tumor cells within the cohort." (PMID 41532361, 2026). "Statistical analysis performed on the data obtained throughout the study (up to day 41) showed a substantial and significant decrease in tumor volume at day 41 in mice in group 2 treated with the lowest dose of CC48 (GP2, 10 mg/kg), compared to the control group (vehicle)." (PMID 40665405, 2025). "GP1 might have anti-tumor activity, while GP2 displayed DPPH scavenging ability at concentration of 2 mg/mL, with a clearance rate of 67.2%." (PMID 37175266, 2023). "GP1 has an anti-tumor effect, while GP2 has a scavenging effect on DPPH." (PMID 37175266, 2023).